CXCR2 (C-X-C motif chemokine receptor 2)
Diseases named in the same sentence as CXCR2 in open-access papers (continued):
Sharing a sentence is not in itself a finding about the gene and the disease.
cholestasis (4 papers, 2014 to 2024). Impairment of the bile flow caused by obstruction within the liver, or outside the liver in the bile duct system. "Among the microbiome changes, the population of A. lactolyticus in mice carrying the genetic inactivation of Cxcr2 was associated with a resistance to the experimental phenotype of biliary atresia, expressed as decreased cholestasis, biliary injury, and improved long-term survival." (PMID 28763485, 2017). "We found that the exposure of Cxcr2-/- mice to SMZ/TMP suppressed cholestasis, decreased the incidence of biliary obstruction, and improved survival." (PMID 28763485, 2017). "The statistical link of Anaerococcus lactolyticus with the group of Cxcr2-/- mice having improved cholestasis and outcome points to a potential role of this bacteria in ameliorating the outcome of biliary atresia." (PMID 28763485, 2017). "The maternal exposure to SMZ/TMP significantly lowered the incidence of jaundice and bile duct obstruction and resulted in improved survival, especially in Cxcr2-/- mice." (PMID 28763485, 2017). "Taking these findings into account, it seems likely that the CXCR2-mediated feedback mechanism described here may be relevant at least for the part of inflammation-induced cholestasis mediated by IL-1β." (PMID 39680527, 2024). "Notably, the inactivation of Cxcr2 alone induced a similar switch, with the additional exposure of Cxcr2-/- mice to SMZ/TMP enriching the bacterial signature with Corynebacterium, Anaerococcus and Streptococcus in those mice with improved cholestasis and survival." (PMID 28763485, 2017).
demyelination (4 papers, 2010 to 2024). "In various models of CNS demyelination and inflammation, CXCR2 has been shown to have enigmatic roles during recovery and repair." (PMID 20596532, 2010). "Furthermore, the role of CXCR2 in myeloid and nonmyeloid cells in association with the destruction and repair of myelin has been demonstrated in an animal model of demyelination." (PMID 26738635, 2016). "It will be important to analyze the effects of selectively ablating CXCR2 on oligodendroglia during JHMV-induced demyelination, while simultaneously manipulating the cellular sources of ELR-positive chemokines in the CNS that may promote neuroprotection during chronic JHMV-induced disease." (PMID 24987333, 2014).
endometrial cancer (4 papers, 2009 to 2023). Primary or metastatic malignant neoplasm involving the endometrium (mucous membrane that lines the endometrial cavity). "In conclusion, CCL2 rs4586, CCL5 rs2107538 and rs2280789, and CXCR2 rs1126580 demonstrated significant associations with an increased risk of endometrial cancer." (PMID 38001676, 2023). "CCL2 rs4586, CCL5 rs2107538 and rs2280789, as well as CXCR2 rs1126580, seem to be significantly associated with an increased risk of endometrial cancer in the population of Polish women." (PMID 38001676, 2023). "Our study demonstrated that both the AA homozygotes in CCL5 rs2107538 and the GA heterozygotes in CXCR2 rs1126580 had significantly been associated with an increased risk of endometrial cancer." (PMID 38001676, 2023). "For the CXCR2 SNP, the G and A alleles were differentially distributed among the various grades and stages of endometrial cancer (p = 0.043 and p = 0.034, respectively)." (PMID 38001676, 2023). "The reported case-control study of genetic associations was designed to establish the role of selected single nucleotide polymorphisms (SNPs) of the CCL2, CCL5, CXCL8, and CXCR2 genes in the onset and progression of endometrial cancer." (PMID 38001676, 2023). "Further research would be justified, regarding the involvement of the rs1126580 polymorphism in the altered CXCR2 expression in endometrial cancer and in the disease prognosis, while its outcomes could bring highly promising results." (PMID 38001676, 2023). "Moreover, the CXCR2 expression was positively associated with the endometrial cancer grade, while being inversely associated with disease-free survival (DFS)." (PMID 38001676, 2023). "Similarly, it was observed that the women who were GA heterozygous for the CXCR2 SNP had an approximately threefold higher risk of endometrial cancer (OR 3.03 95% CI 1.64–5.59 in the codominant model and OR 3.21 95% CI 1.79–5.73 in the overdominant model, p ≤ 0.001)." (PMID 38001676, 2023). "In this case-control study, we aimed to identify the possible associations between selected single nucleotide polymorphisms (SNPs), localized in the CCL2, CCL5, CXCL8, and CXCR2 genes, and the onset and progression of endometrial cancer." (PMID 38001676, 2023). "Significant relationships with endometrial cancer were demonstrated, both for CCL2, CCL5, and CXCL8 chemokines and for the chemokine receptor CXCR2." (PMID 38001676, 2023). "Although little is known of the role of CXCL8 in endometrial cancer, dysregulated CXCL8 and CXCR2 expression has recently been proposed to play a role in other endometrial disorders such as endometriosis." (PMID 19819266, 2009). "Of note, an increased expression of CXCR2 was observed in endometrial cancer tissues compared to non-cancerous endometrial controls." (PMID 38001676, 2023). "The H-W equilibrium was observed for IL8 −738 T>A and CCL5 351 A>G SNPs among all the studied women, as well as for CXCR2 1440 G>A and CCL5 −403 G>A polymorphisms, among the patients with endometrial cancer and non-cancerous individuals, respectively (p ≤ 0.050)." (PMID 38001676, 2023). "Considering endometrial cancer, a significant relationship was noted between its incidence and pathogenesis on the one hand and CCL2, CCL5, and CXCL8 chemokines, and their selected receptors, including CCR2 (the receptor for CCL2) and CXCR2 (the receptor for CXCL8) on the other." (PMID 38001676, 2023). "Furthermore we have shown that CXCL8 immunolocalised to the same cellular compartment in endometrial adenocarcinomas as the FP receptor and CXCR2 (the receptor for CXCL8) and that CXCL8 expression and release is regulated in endometrial carcinoma explants ex vivo by PGF2α via the FP receptor." (PMID 19819266, 2009).
gout (4 papers, 2020 to 2025). A condition characterized by painful swelling of the joints, which is caused by deposition of urate crystals. "The CXCR2 gene rs2230054 is related to the susceptibility of gout in Chinese men." (PMID 35116032, 2021). "Here we show that CXCL5 activates CXCR2 expressed on nociceptive sensory neurons to drive gout pain and inflammation." (PMID 38627393, 2024). "The study found that the CXCR1 gene rs2234671 and CXCR2 gene rs1126579 in the gouty arthritis group were not related to the susceptibility of gout in Chinese men." (PMID 35116032, 2021). "We confirmed CXCR2 expression in human dorsal root ganglion neurons and CXCL5 level upregulation in serum from male patients with gouty arthritis." (PMID 38627393, 2024).
head and neck cancer (4 papers, 2019 to 2023). A primary or metastatic malignant neoplasm affecting the head and neck. "SX-682, for example, is an orally bioavailable CXCR2 inhibitor that blocks MDSC accumulation and promotes NK cell activation in head and neck cancer models." (PMID 37210553, 2023).
inflammatory bowel disease (4 papers, 2017 to 2024). A spectrum of small and large bowel inflammatory diseases of unknown etiology. "Furthermore, our results indicate that dysbiosis might affect the susceptibility to infection by other organisms or inflammatory bowel disease by altering neutrophil recruitment or function, by suppressing CXCR2 expression." (PMID 28817707, 2017).
ischemia (4 papers, 2013 to 2025). A hypoperfusion of the BLOOD through an organ or tissue caused by a PATHOLOGIC CONSTRICTION or obstruction of its BLOOD VESSELS, or an absence of BLOOD CIRCULATION. "This past study demonstrated an increase in total lung CXCL2 within the first day after the onset of ischemia and an inhibitory effect of anti-CXCR2 on bronchial angiogenesis." (PMID 23776670, 2013). "It exerts its effects on neutrophils via two different cell surface receptors initially named as CXCR1 and CXCR2, mediating and regulating leukocyte recruitment and activation at sites of inflammation, followed by ischemia, promoting leakage, and neovascularization." (PMID 36845092, 2023). "CXCR2 does not participate in the ischemia-induced brain injury because CXCR2 antagonists did not improve outcome despite an increase in CXCR2 protein and mRNA levels in microglia cells." (PMID 27635404, 2016).
myelodysplastic syndrome (4 papers, 2017 to 2024). A clonal hematopoietic disorder characterized by dysplasia and ineffective hematopoiesis in one or more of the hematopoietic cell lines. "Elevated expression of IL-8 and CXCR2 was found in stem and progenitor cells isolated from AML and myelodysplastic syndrome (MDS) patients." (PMID 33381455, 2020).
myelofibrosis (4 papers, 2022 to 2024). A partial or complete replacement of the bone marrow stroma by fibrous tissue. "The inhibition of CXCL8/CXCR2 presents a promising therapeutic opportunity for intercepting the progression of myelofibrosis in myeloproliferative neoplasms." (PMID 39706835, 2024). "This underscores the importance of CXCL8/CXCR2 in fibrosis progression and suggests that inhibiting this pathway could be a promising therapeutic strategy for managing myelofibrosis." (PMID 38972952, 2024). "Here, we demonstrate that, in addition to high levels of TGF-β, the megakaryocytes from the bone marrow of the Gata1low mouse model of myelofibrosis express high levels of murine (m)CXCL1, the murine equivalent of hCXCL8, and its receptors CXCR1 and CXCR2." (PMID 35392239, 2022). "Since CXCR1/CXCR2 are also activated by CXCL6 and MIP2, we may not formally exclude that altered levels of these two chemokines are also involved in the development of myelofibrosis in our model and that their levels where normalized by treatment with Reparixin." (PMID 35392239, 2022).
neuroblastoma (4 papers, 2019 to 2025). Neuroblastoma (NB) is the most common solid, extracranial childhood tumor. "In the microenvironment of neuroblastoma, the CXCL2/CXCR2 axis enhances the invasiveness of the tumor via the macrophage-derived signal, justifying the rationale of targeting CXCR2 in NB." (PMID 41155662, 2025). "To further explore the involvement of CXCR2 axis in ALS, we investigated its functional biological role in murine hybrid neuroblastoma–spinal cord NSC-34 cells overexpressing human WT and mutant G93A-SOD1." (PMID 37508478, 2023).
neuropathic pain (4 papers, 2017 to 2020). Chronic pain caused by damage to nerve fibers. "Brandolini and colleagues investigated the effect of reparixin, an inhibitor of CXCR1/CXCR2, in the suppression of the development of paclitaxel-induced neuropathic pain in rats." (PMID 32347537, 2020). "Our results obtained in a neuropathic pain model are consistent with other findings, which suggests that CXCR2 is important for nociception transmission." (PMID 31616413, 2019). "Dual inhibitors of CXCR1/CXCR2 were also tested in the oxaliplatin-induced neuropathic pain model." (PMID 32347537, 2020). "Importantly, NVP CXCR2 20 does not influence microglia or astroglia activation, and probably for this reason, this substance is not responsible for increasing opioid analgesia under neuropathic pain." (PMID 31616413, 2019).
neuropathy (4 papers, 2019 to 2023). A disorder affecting the nervous system that manifests with pain, tingling, numbness, and/or muscle weakness. "This shows that the involvement of the CXCR2 pathway is associated with the development of oxaliplatin-induced neuropathy." (PMID 36768178, 2023). "In neuropathy, CXCR2 is upregulated at the spinal cord level in neuronal and nonneuronal cells and locally at the nerve injury site in macrophages and neutrophils." (PMID 37570736, 2023). "In order to further confirm the involvement of Janus kinase 2 (JAK2) downstream of the CXCR2 pathway in the development of oxaliplatin-induced neuropathy, ruxolitinib, a JAK2 inhibitor, was administered to the oxaliplatin-treated mice (n = 5)." (PMID 36768178, 2023). "CXCR2 in the spinal cord, which plays an important role in the development of oxaliplatin-induced neuropathy, and its related ligands, CXCL1, 3, and 5, were analyzed together." (PMID 36768178, 2023). "Based on published data, we suggest that the blockade of CXCR2 signaling may have effective analgesic effects in neuropathy." (PMID 37570736, 2023). "Reparixin and ruxolitinib blocked oxaliplatin-induced allodynia but not vincristine-induced allodynia, which suggests that CXCR2-related pathways are associated with the development of oxaliplatin-induced neuropathy." (PMID 36768178, 2023). "CXCR2 seems to be one of the most significant CXC receptors involved in neuropathy." (PMID 37570736, 2023). "Based on these results and previously published data, we propose that the spinal blockade of CXCR2 signaling may produce efficient analgesic effects under neuropathy." (PMID 31616413, 2019). "CXCL3 exerts its effects via CXCR2 through signaling pathways, such as p38MAPK and ERK1/2, which are known to be important factors in neuropathy." (PMID 37570736, 2023). "Our in vitro experiments were designed to clarify the potential direct effects of CXCR2 and CXCR3 signaling on glial cells, especially since microglia play an important role in the development of neuropathy." (PMID 34681732, 2021). "Our studies have been conducted to identify the similarities and differences between two chemokine receptors, CXCR2 and CXCR3, in neuroimmune processes occurring during neuropathy and to determine which one may become a better target for neuropathic pain treatment." (PMID 34681732, 2021). "Whether or not spinal CXCR2 signaling is involved in the development of CIPN, and if so, whether vincristine- or oxaliplatin-induced neuropathy is related to CXCR2, are the questions that remain." (PMID 36768178, 2023).
oral cancer (4 papers, 2014 to 2022). "In addition, an association between IL-1β and CXCR2 has been reported in oral cancers." (PMID 35626430, 2022).
oral squamous cell carcinoma (4 papers, 2013 to 2025). "constructed the biomimetic nanodrugs by coating dental pulp MSCs' membrane expressing CXCL8 receptor, CXCR2 on the metal‐organic framework loaded with doxorubicin (DOX) to treat oral squamous cell carcinoma." (PMID 40600457, 2025). "In addition, CXC chemokines (including gro-α) that are secreted by endothelial cells can induce tumor cell invasion, whereas the blockade of the gro-α receptor CXCR2 can inhibit the invasion of oral squamous cell carcinoma-3 and Kaposi’s sarcoma cells into endothelial cells." (PMID 24252539, 2013). "Further studies on oral squamous cell carcinoma cells have revealed that IL-1β mediates the formation of the chemokine CXCL1, which leads to a transactivation of EGFR via the G protein-coupled receptor CXCR2." (PMID 34205482, 2021).
pancreatic adenocarcinoma (4 papers, 2017 to 2021). "Dual-blockade CCR2 plus CXCR2 with specific antagonists reduces tumor-infiltrating myeloid cells and enhances chemotherapeutic responses in pancreatic adenocarcinoma patients and animal models." (PMID 31780645, 2019). "Additionally, combination of SB225002 (CXCR2 inhibitor) with RS504393 (CCR2 inhibitor) overcame the compensatory response of myeloid subset, augmented antitumor immunity and improved chemotherapeutic response of FOLFIRINOX in an orthotopic model of pancreatic adenocarcinoma." (PMID 33414786, 2020).
Peri-Implantitis (4 papers, 2023 to 2025). An inflammatory process with loss of supporting bone in the tissues surrounding functioning DENTAL IMPLANTS. "Investigations on CD14 rs2569190, CXCR2, and miR-27a-3p rs895819 polymorphisms suggested possible associations with peri-implantitis risk." (PMID 41373620, 2025). "They discovered the involvement of inflammation-promoting fibroblasts and a predominance of CXCL8+ fibroblast-CXCR2+ neutrophil interactions in peri-implantitis compared to periodontitis, underlining the enhanced host response in peri-implantitis." (PMID 40486514, 2025). "Our data are in agreement with the study reporting that the CXCR2 gene rs2230054 polymorphism is associated with peri-implantitis susceptibility in the Chinese Han population, and it was established that the CT genotype of rs2230054 serves as a risk factor for the occurrence of peri-implantitis." (PMID 38544825, 2024).
pneumococcal infection (4 papers, 2017 to 2025). Infections with bacteria of the species streptococcus pneumoniae. "Consistent with previous findings, our study revealed that pharmacologically induced CXCR2 LOF with navarixin exhibited increased susceptibility to Streptococcus pneumoniae infection, evidenced by increased bacterial load in the lungs, elevated mortality, and decreased overall survival." (PMID 41451234, 2025). "Therefore, we finally sought to investigate whether our pharmacologically induced CXCR2 LOF mice also display increased susceptibility to Streptococcus pneumoniae infection and whether CXCR4 antagonism could mitigate this susceptibility." (PMID 41451234, 2025). "The significance of this early innate response is exemplified by the finding that CXCR2 knockout mice that recruit significantly fewer neutrophils and exudative macrophages during pneumococcal infection, display a major defect in bacterial clearance." (PMID 35273509, 2022). "The role of CXCR2 is based on the findings that recruitment of neutrophils to the lungs following Streptococcus pneumoniae infection is reduced by CXCR2 ablation." (PMID 28928749, 2017).
serous ovarian cancer (4 papers, 2016 to 2022). "Collectively, this study demonstrated that IL‐8 and IL‐8 receptors CXCR1 and CXCR2 were up‐regulated in advanced ovarian serous cancer tissues." (PMID 31793192, 2020). "In this study, we found that IL‐8 and its receptors CXCR1 and CXCR2 were up‐regulated in advanced ovarian serous cancer tissues." (PMID 31793192, 2020). "Moreover, IL-8 and its receptors (CXCR1 and CXCR2) are upregulated in advanced serous ovarian cancers." (PMID 35867729, 2022). "Furthermore, overexpression of CXCR2 had poor overall and disease-free survival of patients with high-grade serous ovarian carcinoma." (PMID 27723802, 2016). "First, we examined IL‐8, CXCR1 and CXCR2 expression in samples of ovarian serous cancer tissue and found the IL‐8, CXCR1 and CXCR2 were highly expressed in high‐grade ovarian serous cancer tissues than in low‐grade ovarian serous cancer tissues." (PMID 31793192, 2020).
skin cancer (4 papers, 2016 to 2025). "We found that the frequency of PMN-MDSC was significantly decreased in metastatic LN and showed a tendency for the reduction in primary skin tumors from mice treated with the CXCR2 inhibitor as compared to control group." (PMID 33578808, 2021). "In addition, CXCR2 expression was significantly more frequent on PMN-MSDC infiltrating distant metastases as compared to those accumulated in primary skin tumors." (PMID 33578808, 2021).
type 1 diabetes (4 papers, 2015 to 2024). "Mouse Cxcr1 and Cxcr2 genes are located in an insulin-dependent diabetes genetic susceptibility locus." (PMID 26230114, 2015). "The type 1 diabetic mouse was transplanted intradermally at the wound periphery with 1 × 106 cells/wound of MSC with stable Cxcr2 overexpression and/or silencing groups as well as their respective controls." (PMID 38597972, 2024). "In type 1 diabetes patients with transplanted pancreatic islets, elevated circulating CXCL8 levels are detected, and CXCR1/CXCR2 activation has been associated with mediating damage to and reducing survival of these islets." (PMID 36725964, 2023). "In another murine model, a CXCR1/CXCR2 antagonist prevented and reversed also type 1 diabetes, for which clinical trials are currently ongoing (vide infra)." (PMID 36725964, 2023). "The MIF/CD74 signaling pathway promotes macrophage-mediated inflammation in type 1 diabetes, and MIF controls the recruitment of inflammatory cells via chemokine receptors CXCR2 and CXCR4." (PMID 34445689, 2021).